CD4 (CD4 molecule)
Diseases named in the same sentence as CD4 in open-access papers (continued):
Sharing a sentence is not in itself a finding about the gene and the disease.
tumor (continued). "However, we also explored the frequencies of CD3 + CD4 + PD-1 + Tim-3 + T cells and CD3 + CD8 + PD-1 + Tim-3 + T cells between neoplasms group and normal control." (PMID 36991376, 2023). "Besides, CTLA-4 is constitutively expressed on CD4+ Tregs, later work demonstrated that the CTLA-4 antibody acted, at least partially, through Fcγ receptor (FcγR)-dependent depletion of tumor-infiltrating Treg cells." (PMID 37691932, 2023). "Primed CD4+ T cells activate B and CD8+ T cells to kill tumor cells." (PMID 36797245, 2023). "Functional analyses revealed the presence of tumor-reactive host T cells in lymph nodes and spleens after antigen re-stimulation in vitro, with SIVET and vaccine-only conditions showing higher percentages of IFN-γ expressing host CD4+ and CD8+ T cells." (PMID 37322053, 2023). "Our results indicate that CD4+ CTLs might be as pivotal to tumor immunity as CD8+ CTLs, and that CD4+ CTLs also interact with B cells through physical conjugation." (PMID 38077321, 2023). "Studies have demonstrated that PDL1 + T cells have various tolerogenic effects on tumor immunity through different mechanisms, including induced STAT3-dependent ‘back-signaling’ in CD4 + T cells, inhibition of effector T cells via the PDL1-PD1 axis, and engagement with PD1 + macrophages." (PMID 37777797, 2023). "Although the CD4/CD8 ratio of tumor-draining and non-dLNs was comparable, the frequencies of naïve T cells were decreased and those of effector memory T cells were increased in Ccl21a-KO dLNs." (PMID 37664721, 2023). "Moreover, we performed CD4 and CD8 depletion assays to further elucidate which TILs play the pivotal role in tumor regression." (PMID 37024504, 2023). "Furthermore, the infiltration density of CD8+ TIL, CD4+ TIL, and Foxp3+ TIL in liver metastases was also significantly decreased compared to the primary tumor." (PMID 37828574, 2023). "Additionally, IL-17, a proinflammatory cytokine primarily produced by CD4+ Th17 cells, exerts an antitumor effect by recruiting CD4+ T, CD8+ T, and NK cells to the tumor site, enhancing NK cell activity." (PMID 37416781, 2023). "There were no clinical signs or tumor development in vaccinated/challenged birds with depleted CD4+ or CD8+ T cells." (PMID 36992357, 2023). "We found that the untreated tumor-bearing mice had a very low T cell population, 3-fold less than healthy naive mice, whereas the JOL2888 treatment elicited a T cell response, with 13% and 8% of CD4+ and CD8+ cells, respectively." (PMID 37941832, 2023). "Considering the involvement of hypoxia in the immunosuppressive microenvironment of tumors, we provided evidence that deleting the transcriptional activity of HIF-1α decreased the tumor growth of a melanoma mouse model and increased the infiltration of CD45+, NK, CD4+, and CD8+ cells." (PMID 37443821, 2023). "Following immunization, strong cellular immunity was observed in spleen and lymph node cells, including high activity of IFN-γ+CD4+ T cells, IFN-γ+CD8+ T cells, cytotoxic T lymphocytes (CTLs) and cytokine excretion, leading to significant tumour growth suppression and prolonged survival." (PMID 36980527, 2023). "Interestingly, although anti-PD-1 alone modestly affected the levels of tumor-infiltrating lymphocytes (TILs), the combination of anti-PD-1 treatment and VPRBP depletion induced a marked increase in TILs, including CD4+, CD8+/granzyme B+ T cells." (PMID 37024504, 2023). "As the prognosis of patients with MM is improved with higher CD8+ T cells in the TILs,46 the numbers of human CD45+ cells, CD3+ T cells, CD4+ T cells, CD8+ T cells, and T regulatory cells per gram of tumor tissue in each treated group was analyzed via flow cytometry." (PMID 36816748, 2023). "Though the activated CD4 T cell and activated CD8 T cell expression increased under such a situation, it could represent positive feedback from a tumor attack." (PMID 37025600, 2023).
tumor (continued). "Thus, we evaluated the level of intracellular IFN-γ in both CD4 and CD8 T cells in spleen, lymph nodes (LN), tumor-draining lymph nodes (TDLN) and tumors from mice in each treatment regimen." (PMID 37046612, 2023). "Mechanistic investigation revealed that combination therapy was capable of reducing the proportion of MDSCs in the spleen and blood while promoting their maturation, which resulted in increased Th1-dominant CD4+ T-cell differentiation and enhancement of CD8+ T-mediated tumor killing." (PMID 37108179, 2023). "Therefore, CD4+ CTL are most commonly reported from chronic or latent viral infections and tumor diseases, which is the focus of this review." (PMID 37965314, 2023). "Thus, compared with CD4+ TEGs, CD8+ TEGs were shown to be more potent tumor-targeting cells with profound serial killing capacity." (PMID 35879361, 2023). "documented that combining IL-2 with anti-PD-1 helps overcome tumor resistance to ICIs in mice by reactivating intratumoral CD8+ T cells rather than CD4+ Treg cells." (PMID 38022654, 2023). "These migratory cDC (mDC) have been shown to drive and direct CD4+ and CD8+ T cell responses in homeostasis, infection and tumour settings, with both migratory cDC1 (mDC1) and migratory cDC2 (mDC2) being critical for the initiation of robust anti-viral and anti-tumour responses." (PMID 37478193, 2023). "Moreover, the combination of anti-CD40/PD-1 therapy led to an increased number of CD4+ and CD8+ T cells, CAF cells and myeloid cells in the tumor, which were shown to drive immunotherapy resistance in CCA." (PMID 36980187, 2023). "Research indicates that CD4+ T helper cells, CD8+ cytotoxic T cells, NK cells, N1 neutrophils, M1 macrophages and DCs are protective against tumour growth, and that an effective interaction of these subsets is needed to protect the host against a developing tumour." (PMID 36980527, 2023). "At the tumor front, increased cell-cell interactions between regulatory CD4+ T cells and non-proliferating tumor cells were indicative of well differentiated tumors." (PMID 38125025, 2023). "Kruskal–Wallis non‐parametric tests showed patients with high stromal expression of STAT3 had reduced CD4+ T‐cell counts within the tumour (p = 0.001) but not the stroma (p = 0.279) in triple negative cases." (PMID 37199043, 2023). "Tumor-infiltrating CD8+ and CD4+ T cells also expressed high levels of A2AR and notably this expression was significantly higher than observed with CD8+ or CD4+ T cells isolated from spleen or draining lymph nodes." (PMID 37914685, 2023). "MEX3B and MEX3C were positively correlated with tumour purity, CD8+ T cells and CD4+ T cells." (PMID 36507941, 2023). "In contrast to the significantly increased tumor burden in Chatfl/fl; Cd4-cre mice, HCC progression was not exacerbated in Rag1–/– mice but instead was alleviated." (PMID 37640929, 2023). "Activation markers CD25 and CD69 were upregulated on CD4+ T cells in the presence of PDL1-BiTE/tumor, rather than PBLs/tumor." (PMID 39282109, 2023). "Treatment of tumours consisting of HCmel12 CRISPR-control (ctrl) and HCmel12 Trp1-KO mixtures demonstrated that TRP-1 CD4+ T cells also exerted substantial bystander killing activity, but could not prevent the outgrowth of HCmel12 Trp1-KO cells in all mice." (PMID 37316667, 2023). "We found that memory CD4 T cells and resting mast cells were also obviously increased in the ELANE high-expression group; however, the tumor infiltration of these cells was related to poor prognosis in tumor patients." (PMID 37596368, 2023). "TCR-engineered CD4+ T cells carrying an HLA-DP4-restricted TCR for the cancer-testis antigen MAGE-A3 demonstrated safety and efficacy in inducing objective tumor regression across multiple cancer types, validating the potential of modified MAGE-A3-specific CD4+ T cells." (PMID 37892995, 2023).
tumor (continued). "The presence of activated CD4 T cells, γδ T cells, and NKT cells may indicate that the immune system is trying to recognize and attack tumor cells." (PMID 37759912, 2023). "Tumor Immune Estimation Resource (TIMER; cistrome.shinyapps.io/timer) helps to calculate the levels of six tumor-infiltrating immune subsets, namely B cell, CD4+ T cell, CD8+ T cell, neutrophil, myeloid dendritic cell and macrophage." (PMID 38157255, 2023). "CD4+ T cells are also important for mounting anti-tumor immune responses by recognizing Ags presented on MHC class II molecules of antigen-presenting cells (APCs), but also on tumor cells." (PMID 37047709, 2023). "Moreover, Fn infection reduced the αPD-L1-mediated increase in the CD4+, CD8a+ and GZMB+ CD8a+ T-cell populations in the tumor region." (PMID 37723150, 2023). "We selected CCL19 as APC binding molecule for further characterization based on its ability to increase the immunogenicity of the fused neoepitopes inducing a balanced neoepitope-specific CD4+ and CD8+ T-cell responses and leading to complete tumor rejection in a prophylactic setup." (PMID 37720215, 2023). "In this study, we examined the infiltrating level of TIL, CD4+TIL, and CD8+TIL in naïve and post‐chemotherapy NCT‐NSCLC tumor tissue specimens, and explored their prognostic value in patients with NCT‐NSCLC, both naïve and post‐chemotherapy tumor tissue specimens came from the same patients." (PMID 36789099, 2023). "We found that major pathology response (MPR), pathological tumor, node, and metastasis stage post‐NCT (ypTNM), post‐chemotherapy TIL, post‐chemotherapy CD8+TIL, naïve CD4+TIL, naïve CD4+/CD8+TIL ratio, and change of CD4+TIL are prognostic factors of NCT‐NSCLC." (PMID 36789099, 2023). "In mouse models, antigen-loaded GO-AlO(OH) nanocomplexes increased antigen absorption and boosted the activation of DCs, eliciting greater antigen-specific IgG titers, producing a strong CD4+ and CD8+ T lymphocyte response, and suppressing the development of melanoma tumor." (PMID 37047572, 2023). "As cDC1s and cDC2s contribute to antitumor immunity in part through induction of tumor-reactive CD8 + and CD4 + T cells, respectively, further investigation into the specific contribution of these cells on T cell differentiation during tumor growth and immunotherapy is of interest." (PMID 36472588, 2023). "Early tumor infiltration by activated CD4+ T-cells induced by Lipo-MP-LPS is not due to a direct effect, since lymphocytes do not express TLR4." (PMID 37760603, 2023). "SEMA3A overexpression was associated with an increase in the recruitment of CD49b+ NK cells and CD3+ T cells to the tumour and a higher ratio of CD8+ to CD4+ T cells, and with a significant reduction in tumour volume (61%) and weight (60%) compared to control tumours." (PMID 37685898, 2023). "Agonistic anti-CD40 cross-linking antibody fully restored CD8+ T cell-mediated tumor rejection in the complete absence of CD4+ T cells, suggesting that providing Th1-based cell help is a key feature for effective therapy even in the absence of CD4+ Tfh." (PMID 37655661, 2023). "It is known that CD4+ T helper cells and CD8+ cytotoxic T cells protect against tumor growth and that a coordinated and balanced interplay between these subsets is required to protect the host from a developing tumor." (PMID 37345025, 2023). "Genetic ablation of Klf5, FZU00,004 (a KLF5 inhibitor) and CEL failed to reduce the frequency of tumor-infiltrating Tregs (Cd4+Cd25+Foxp3+ T cells), but Klf5 depletion increased the number of Cd3+Cd8+ T cells and increased the Cd3+Cd8+/Treg ratio." (PMID 36923542, 2023). "Previous studies have confirmed that trastuzumab inHER2-positive gastric cancer patients can modulate the tumor microenvironment (TME), via upregulating PD-1 and PD-L1 expression, expansion of tumor-specific CD4 and CD8 T cells, and enhancing the antitumor effects of immune checkpoint inhibitors." (PMID 37274273, 2023).
tumor (continued). "According to the literature, CD3+, CD4+ and CD8+ are categorized as tumour-infiltrating." (PMID 37762967, 2023). "CD4+ T cells play an important role in the tumor microenvironment, and there is no direct evidence that CD4+ T cells directly inhibit tumor angiogenesis." (PMID 37342362, 2023). "In addition, TIMER analysis revealed that MEX3B and MEX3C were positively related to tumour purity and CD8+ T cell and CD4+ T cell infiltration." (PMID 36507941, 2023). "Furthermore, a substantial accumulation of T cells, including CD4+ and CD8+ T cells, was observed in Cluster B, resulting in significantly higher ImmuneScore and StromalScore compared to Cluster A, despite lower tumor purity." (PMID 37000317, 2023). "Interestingly, patients with a baseline PD-L1 combined positive score (CPS) of 5 or higher, low tumor CD68 and high CD4 protein levels had significantly improved ORR, PFS, and OS." (PMID 38269272, 2023). "However, no significant results between the features of stroma and infiltrating immune cells were found for CD4+, CD8+, and CD206+ cells in the whole tumor." (PMID 37405518, 2023). "CD40 and CD40L interact to mediate anti-tumor immune responses by increasing immunogenic cell death (ICD) of tumor cells, activating antigen-presenting cells, producing proinflammatory factors and stimulating CD4+ and CD8+ T cells." (PMID 37666809, 2023). "al., safety was established and, though non-significant, there was a trend of improved OS in patients with elevated peripheral CD4+ T cells and hypermutated tumor status not taking steroids at the time of atezolizumab monotherapy." (PMID 37568717, 2023). "Actually, that CD4 and CD8 T-cell composition in both the spleen and tumor varied among models." (PMID 37207216, 2023). "They further show the anti-tumor immune response in Nt5e depleted tumors was associated with CD4+ and CD8+ T cells expressing IFN γ and showed the response was dependent on CD4+ T cells, but not CD8+ T cells." (PMID 37187740, 2023). "Previous studies have shown that TAMs in HCC tumor stroma produce various proinflammatory cytokines, including TNF-α, IL-β, IL-6 and IL-23, which induce the expansion of CD4+ Th17 cells, according to the overexpression of PD-L1, CTLA4 to inhibit antitumor immunity." (PMID 37745297, 2023). "Similarly, expression levels for various immune cell markers such as CD3, CD4, and CD8 were highest in the Brca1-null tumours." (PMID 38017453, 2023). "In summary, we characterize a model in which human CD4 CTLs play an independent, essential, and non-redundant role in tumor control." (PMID 37185301, 2023). "To explore whether the immune cell subsets of tumor tissues with high expression of ICOSLGTCs in OSCC patients changed, we determined the ICOSLG, CD4, CD8, CD19, CD68 and Foxp3 level of tumor centers and infiltration fronts in serial sections." (PMID 37842091, 2023). "CD4+ and CD8+ T cell populations separated within both the blood and the tumor samples (bottom)." (PMID 37217652, 2023). "We chose to analyze five immune markers (CD3+, CD4, CD8+, CD19+, and CD163) because they represent the main immune cell types (cytotoxic and regulatory T cells, B cells, and macrophages) and play key roles in tumor immunity." (PMID 37090736, 2023). "TIM-3 is expressed on the surface of different kinds of T-cells (CD4+ cells, CD8+ cells, T-reg cells, and Th17 cells), but also on the surface of APCs, and it exerts its activity upon binding the galectin-9 expressed on tumor cells." (PMID 37835378, 2023). "The T‐lymphocyte subsets in the peripheral blood of tumor patients were abnormal, including the significant decrease of CD3+ and CD4+ T cells, the significant increase of CD8+ T cells, and the significant decrease of the CD4+/CD8+ ratio." (PMID 37904699, 2023). "CD4+ and CD8+ effector T lymphocytes (CD3+/ CD44+/ CD62L−) were measured in spleen, DLNs, and tumor tissues, considering their relevance in the elimination of solid tumors and their value for tumor prognosis." (PMID 37736849, 2023).
tumor (continued). "Additionally, responding patients had a lower tumor burden and displayed the expression of chemokine receptors (CCR7, CCR6, CXCR4, CXCR3, and CXCR5) on CD4+ T cells." (PMID 37174069, 2023). "However, several others demonstrated that both CD8+CD137+ and CD4+CD137+ T cells contribute, with similar efficacy, in responses against tumours." (PMID 37108276, 2023). "At the tumor front, regulatory CD4+ T cells interacted more closely with non-proliferating tumor cells in lower grade compared to higher grade tumors." (PMID 38125025, 2023). "The identified PhenoGraph clusters were assigned to seven major populations: tumor cells (panCK+), CD4+ T cells (CD45+CD3+CD4+), CD8+ T cells (CD45+CD3+CD8+), B cells (CD45+CD20+), blood vessel (CD31+ and/or aSMA+), fibroblasts (collagen+), and myeloid cells (CD45+CD14+)." (PMID 38125025, 2023). "Notably, A2AR expression was highly expressed in all subsets except for B lymphocytes, with NK cells, CD4+ lymphocytes and CD8+ lymphocytes together constituting over 50% of A2AR+ cells within the tumor." (PMID 37914685, 2023). "al., assessed total T cells, PD1 on CD4+ and CD8+ T cells; and PD-L1 on stromal and tumor cells." (PMID 37104271, 2023). "Moreover, miR-155 T-cell-conditional knockout mice exhibit enhanced tumor growth and reduced IFN-γ-expressing CD4+ and CD8+ T cells." (PMID 36980512, 2023). "CD4+ T cells do not typically exert cytotoxic functions, but rather promote inflammation and tumor reactivity by cytokine mediated activation of CD8+ T cells." (PMID 37122741, 2023). "CD4 + iNKT cells, unlike their CD4- counterparts, can boost tumor growth by inhibiting the cytotoxicity of CD8 + T cells and promoting Th2 cytokine production in HCC." (PMID 36773210, 2023). "Interestingly, we found a close association between higher TMB and smaller nearest distance of CD4+ and CD8+ T cells to tumor cells in baseline tumor tissues." (PMID 37275884, 2023). "In various types of cancer, including melanoma, MDSCs were shown to induce tumor growth and progression by promoting the immunosuppressive TME, e.g., by inhibiting NK cells, CD4+ T cells and CD8+ T cells, and stimulating the activity of regulatory T cells (Tregs)." (PMID 37887285, 2023). "Docetaxel + NHS-IL-12 combination therapy failed to provide tumor control following CD4+ T cell depletion (p = 0.9968), with few animals capable of controlling tumor growth (number of animals with less than 50mm3 reduced from 3/7 to 1/5)." (PMID 37166485, 2023). "Apart from tumor-expressed lncRNAs that impair effector CD8+ T cells, several lncRNAs have been described that induce an immunosuppressive TME by altering tumor-infiltrating CD4+ T cells, Tregs, γδ T cells and NKT cells." (PMID 37346034, 2023). "Furthermore, under NIR laser irradiation, CD4+ and CD8+ T cells in tumors were increased after MPCZ NPs treatment, confirming that MPCZ NPs treatment can activate the anti-tumor immune response based on macrophages and T cells." (PMID 37061706, 2023). "On the other hand, even in the absence of CD8+ T cells, CD4+ T cells can also kill tumor cells directly by mechanisms involving IFN-γ." (PMID 38106403, 2023). "The negative correlation between SEC61G expression levels and the infiltration of CD4+ T cells, CD8+ cells, and NK cells in OSCC patients indicates that SEC61G may be involved in immune evasion mechanisms employed by the tumor." (PMID 37893092, 2023). "Expression analysis of the immune checkpoint PD-1 on TILs showed a significantly increased number of PD-1+CD4+ and PD-1+CD8+ T cells in TDLNs at early stage of tumor development (T2), and of PD-1+CD8+ in tumor after 8 days (T8) of SR59230A, αPD-L1, or their combination treatment compared to control." (PMID 36854895, 2023). "In eMSC-treated mice, primary tumor CD8α+ T-cell percentages significantly increased, but, similarly to total CD3ε+ T-cell percentages, CD4+ T-cell depletion did not affect this increase." (PMID 37928528, 2023).